CXCR4 (C-X-C motif chemokine receptor 4)
Diseases named in the same sentence as CXCR4 in open-access papers (continued):
Sharing a sentence is not in itself a finding about the gene and the disease.
tumor (continued). "In line with this microenvironment-centric strategy, CAR-Ts engineered to co-express CXCR4 demonstrate superior antitumor activity, with improved stromal trafficking and concomitant reductions in MDSC ingress, yielding more durable tumor control than conventional CAR T cells." (PMID 41281758, 2025). "In our study, we found that the HP infection score in the tumor group was notably higher than that in the normal group and screened five key prognostic genes (CTLA4, CPVL, EMB, CXCR4, and FAM241A) from the HP infection–related DEGs in STAD to establish a riskscore model." (PMID 39886652, 2025). "CXCR4 is a hypoxia- and hypoxia-inducible factor (HIF)-induced receptor for the chemokine CXCL12/stromal cell-derived factor-1 (SDF-1), and is therefore a good marker for VHL mutant tumor cells." (PMID 39920694, 2025). "Furthermore, we found that, compared to tumor tissues, T cell subsets in normal tissues were more regulated by iCAFs and apCAFs through pathways such as CXCL12-CXCR4 and MIF-(CD74+CXCR4)." (PMID 40740774, 2025). "In this environment, CXCL12, secreted by cancer-associated fibroblasts (CAFs) and mesenchymal stem cells, binds to the CXCR4 protein expressed on TNBC cells and immune cells, leading to the activation of signalling pathways, which promote an immunosuppressive tumour environment." (PMID 41002447, 2025). "Experiments in mice suggested that the blockade of the homing receptor (CXCR4) and chemokine receptor (CCR4/CCR8) may inhibit Treg infiltration and tumor homing." (PMID 40427000, 2025). "SPHK1, and thus S1P production, positively correlated with CXCR4 expression in COAD tumor samples, but not in normal tissue." (PMID 40155684, 2025). "Moreover, AMD3100 is receiving interest as an anti-cancer agent that disrupts the CXCR4/CXCL12 chemokine receptor interaction between neoplastic cells and their microenvironment in tumor progression and metastasis." (PMID 40142155, 2025). "CXCR4 overexpression promotes tumor spheroid formation and epithelial-mesenchymal transition (EMT), whereas CXCR4-knockout murine models exhibit significantly smaller NSCLC tumor lesions compared to CXCR4-high counterparts." (PMID 40607416, 2025). "Together, these data suggest that specifically and simultaneously targeting CXCR4 and S1P5 activity in the tumor microenvironment (TME) could be a beneficial strategy to unleash full cytotoxic potential of cytotoxic NK effector cells in the tumor." (PMID 40155684, 2025). "Preclinical studies show that CTCE-9908, another CXCR4 inhibitor, competitively inhibits the interaction between the CXCR4 receptor and its ligand SDF-1α, which blocks the function of CXCR4, thus suppressing tumor growth and metastasis." (PMID 40075611, 2025). "Additionally, miR-193-5p acts as a tumour suppressor in CRC and enhances the inhibition of CXCR4 when combined with 5-fluorouracil (5-FU) and oxaliplatin, reducing chemoresistance." (PMID 40307933, 2025). "The CXCL12/CXCR4 axis is indeed a critical pathway for CD8+ T cell trafficking, but emerging evidence underscores the importance of complementary chemokine axes that contribute to immune cell recruitment and spatial coordination in the tumor microenvironment." (PMID 40698080, 2025). "Moreover, triptolide inhibits CXCL12 gene expression within the tumor microenvironment, leading to the suppression of the CXCL12/CXCR4 axis and a reduction in TAM infiltration." (PMID 40490812, 2025). "Intriguingly, the significantly elevated CXCR4 mRNA levels were detected in primary ccRCC tumors without metastases, but not in metastasized tumor, and were correlated with short survival time." (PMID 39920694, 2025). "In-vivo assessment of CXCR4 PET-derived volumetric parameters is prognostic for patient outcome with GEP-NECs and might reflect tumor heterogeneity and aggressiveness." (PMID 38332341, 2024).
tumor (continued). "However, despite the antitumor effect, it is noteworthy that in some cases the ELR− ligands have pro-tumorigenic properties, such as ELR-CXCL12/CXCR4, ELR-CXCL11/12-CXCR7, and ELR-CXCL13/CXCR5, increasing angiogenic and metastatic activities in the tumor." (PMID 39769501, 2024). "The tumor-derived EVs did not carry CXCR4 nor ACKR3 protein, suggesting the transfer of other molecules that induce ACKR3 expression." (PMID 39698539, 2024). "The expression of CXCR3 and CXCR4 has been shown to be downregulated upon activation and antigen exposure, which supports the notion that DP CD8+ T cells with lower expression of CXCR3 and CXCR4 encounter their cognate tumor antigen." (PMID 38335302, 2024). "The nuclear presence of CXCR4 in CRC liver metastasis cells underscores its potential impact not only in cell signaling but also in the gene expression profiles that govern metastatic behavior and tumor aggressiveness." (PMID 39195225, 2024). "Moreover, the conjugation of FITC-CXCR4 to PEG-CdTe-DOX was verified by the green fluorescence on the surface of the CXCR4-PEG-CdTe-DOX-treated U266 cells, which can enhance intracellular drug concentration through actively targeting tumor cells." (PMID 38244066, 2024). "The presented results indicate the significant correlation between the CXCL12, CXCR4, CXCL8/CXCR2, M-CSF, MMP-2, MMP-9 ADAM17, ADAMTS-6, and CLDN7 levels and tumor stage, as well as the clinicopathological parameters of OC, such as the presence of lymph node and/or distant metastases." (PMID 38673838, 2024). "They exhibited distinct spatial organization patterns, and compared to adjacent non-tumor tissues, tumor tissue showed an increased prevalence of CXCR4+ tip cells, yet with SELE+ veins depleted." (PMID 39345334, 2024). "CXCR4, the 7-transmembrane G-protein coupled receptor (GPCR), shows high expression within numerous cells including endothelial cells, lymphocytes, stromal fibroblasts, hematopoietic stem cells, and tumor cells." (PMID 39081954, 2024). "Analysis of stRNA-Seq data revealed a notable enhancement in the interaction intensity between CXCL12 and its predominant receptor CXCR4 on T cells in the IGF2hi tumor, unlike in the IGF2lo tumor." (PMID 39545420, 2024). "Thus, it is reasonable to believe that targeting CXCR4 can antagonize the combination of CXCR4 and SDF-1, remove tumor cells out of the tissue site, and make them more accessible to traditional treatments." (PMID 38244066, 2024). "Similarly, blocking of a subset of TAMs positive for C3AR1, CXCR4, and CSFR1, using either anti-C3a therapy or SB290157 treatment of B16 melanoma mice, resulted in reduced F4/80 infiltration as well as slowed tumor growth." (PMID 39172519, 2024). "However, tumor-infiltrating CD8 + T cells remained low for both AMD3100 and P-BS-CM1 → P-CM2, aligning with previous studies showing CXCR4 blockade alone is insufficient to activate anti-tumor immunity." (PMID 38553476, 2024). "Similarly, an orthotopic tumour mouse model, with locoregional delivery of the TRT would perhaps more accurately recapitulate the clinical scenario of future CXCR4 theranostics used in GBM treatments." (PMID 39008219, 2024). "MIF released from MMP7+ tumour cells activated CD74, CXCR4 and CD44 on immune clusters." (PMID 39187937, 2024). "The circ-0044539-VEGFA-HIF-1α-CXCR4 axis showed minimal intensity in tumor tissues from HCC patients without LNM and obvious upregulation of expression in the tumor tissues of HCC patients with LNM." (PMID 39191749, 2024). "In this study, the proportion of CXCR4 high expression in GEP-NENs G3 tumor diameter ≥5cm group was higher than that in tumor diameter < 5cm group, but the difference was not statistically significant (19.5% vs 15.1%, P = 0.572)." (PMID 38524630, 2024).
tumor (continued). "While taxol treatment even enhanced the SDF-1 expression in MSC, the derived EV/exosome-associated SDF-1 may also contribute at least partially to the activation of the CXCR4 and/or CXCR7 receptors on target cells of several tumor populations." (PMID 39420354, 2024). "This epigenetic modulation by acetylated KLF5 unveils a therapeutic opportunity; the concurrent administration of docetaxel and the CXCR4 inhibitor plerixafor has shown efficacy in curbing ac‐KLF5‐driven bone metastasis and enhancing tumor response to chemotherapy." (PMID 38374872, 2024). "The COMBAT trial assessed combination CXC chemokine receptor 4 (CXCR4) with pembrolizumab in a phase IIa study of patients with metastatic PDAC, having demonstrated in mouse models that CXCR4 may increase T cell tumour infiltration." (PMID 39330013, 2024). "Furthermore, CXCR-4 up-regulation, through TNF-α, mediated tumor cell motility and the production of inflammatory cytokine and chemokine receptors/ligands, including CXCR4." (PMID 39609700, 2024). "The interaction between the BM microenvironment and NB cells is mediated, in part, by the MIF/CXCR4 signaling axis irrespective of the tumor cell biology." (PMID 38730688, 2024). "Additionally, MIF released from DKK1+ tumor cells activated CD74, CXCR4, and CD44 on immune clusters." (PMID 39505867, 2024). "Additionally, residual M2-type TAMs aggregate in the perivascular region through the CXCR4/CXCL12 pathway, secreting factors like VEGF to further facilitate tumor revascularization and recurrent metastasis." (PMID 39531417, 2024). "The results for these tumor types, while included for completeness, do not allow for robust conclusions about CXCR4 expression patterns or the utility of [18F]AlF-NOTA-QHY-04 PET/CT in these cancers." (PMID 39431004, 2024). "In the subsequent analysis of the potential pathways between GrB+ B cells and tumor cells, the most important incoming and outgoing L-R pairs were the signaling complexes, macrophage migration inhibitory factor (MIF) -(CD74 + CXCR4) and lymphotoxin-alpha (LTA)–(LTB + LTBR), respectively." (PMID 38386050, 2024). "Whereas SDF-1 represents the ligand for the chemokine receptors CXCR4 and CXCR7, Western blot analyses were performed to identify expression of these receptors on the different cancer cell lines representing five different tumor entities." (PMID 39420354, 2024). "The PLOD2 + SAA1 + tumor cells could communicate with other cells through ligand-receptor pairs like SPP1-CD44, MIF-(CD74 + CXCR4), and MDK-LRP1." (PMID 38951896, 2024). "Collectively, these findings demonstrate escalated CXCR4 clustering by P-BS-CM1 → P-CM2 can profoundly amplify disruption of downstream pro-survival and pro-metastatic signaling, potentially sealing the metastatic potential of tumor cells." (PMID 38553476, 2024). "Finally, C-X-C chemokine ligand-4 secreted by endothelial cells promotes cancer cells’ transendothelial migration through interaction with C-X-C chemokine receptor type 4 and 7 (CXCR4 and CXCR7) expressed by tumor cells." (PMID 39035739, 2024). "CXCL12 attracts cancer cells by binding to CXCR4, which is expressed on both hematopoietic and non-hematopoietic tumor cells." (PMID 39273290, 2024). "CXCR4 was highly expressed only in tumor tissues, and low or no expression was found in the adjacent tissues." (PMID 38524630, 2024). "This suggests that the TNFR2/CXCR4/CXCL-12 cascade may have a significant impact on the recruitment of immunosuppressive cells, the initiation of cancer, and the proliferation of tumor cells, thereby supporting the development of BC." (PMID 39609700, 2024). "Moreover, CXCR4 and CCR7 interact with their respective ligands chemokine (C-X-C motif) ligand 12 (CXCL12) and chemokine (C-X-C motif) ligand 21 (CCL21), enabling tumor cells to have “chemotaxis” and promoting their metastasis to the intended organs." (PMID 38549934, 2024).
tumor (continued). "According to reports, CXCR4 is highly expressed in B cells 34,35, while DLBCL is a highly malignant tumor originating from B lymphocytes, which may be the reason for the highest uptake of [18F]AlF-NOTA-QHY-04 in DLBCL patients." (PMID 39431004, 2024). "The L–Rs including the MIF-(CD74+CXCR4) and collagen/fibronectin/laminin-CD44 interactions in MTs may create a tumor immunosuppressive microenvironment." (PMID 38414027, 2024). "Similarly, the blockade of both CXCR4 and PD-1 in a murine model of ovarian cancer revealed increased CD4+ and CD8+ T cell tumor infiltration." (PMID 38786066, 2024). "Furthermore, the CXCL12/CXCR4-AKT axis activates the downstream RhoA/ROCK2 pathway, which modulates cell invasion and tumor metastasis." (PMID 39766093, 2024). "Due to tumor immune tolerance and the heterogeneity of the tumor microenvironment, several preclinical risks need to be addressed for the application of CXCL12 treatment and CXCR4+ B cell adoptive transfer." (PMID 39422063, 2024). "Furthermore, the iso-ligand receptors MIF-(CD74+CXCR4) and MIF-(CD74+CD44) regulate T/NK cells, potentially facilitating tumor cell evasion of immune surveillance." (PMID 39712016, 2024). "However, chemokine receptor CXCR4 has a sole natural ligand, CXCL12, and, in cancer, this interaction can facilitate metastasis to secondary sites, promote tumour growth, and therapy resistance." (PMID 39204345, 2024). "CXCR4 may also influence the PDAC tumor immune microenvironment (TIME) and the CXCR4 inhibitor could improve the prognosis of PDAC by regulating the TIME." (PMID 38983932, 2024). "However, some other targets like migrating molecule CXCR4, integrin receptors, HER2 receptor, bone cells and even tumour niche are reported." (PMID 39231955, 2024). "The results indicate that the anti-CXCR4-NaGdF4 NDs have certain biotherapeutic effects, which could significantly prolong the survival time of MDA-MB-231 tumor-bearing mice." (PMID 38982161, 2024). "Notably, in tumor-targeted therapy, both curcumin and a novel dimanganese complex (FMSP) have been observed to downregulate CXCR4, thereby promoting the generation of ROS and inhibiting the activation of the STAT3 pathway." (PMID 38920657, 2024). "Notably, tumor cells positive for CXCR4 migrate along the CXCL12 concentration gradient to distant organs exhibiting high CXCL12 expression, thereby facilitating tumor metastasis." (PMID 38920657, 2024). "In addition, preclinical studies showed that both pharmacological inhibition of CXCR4 and genetic ablation of CXCL12-producing CAFs led to a rapid accumulation of CD8+ T cells within the tumor and reduced tumor growth." (PMID 38182756, 2024). "Despite extensive research on the functions of CXCR4 expressed in tumor cells, limited attention has been paid to CXCR4 expressed in the stroma in OSCC, and no reports have confirmed its expression specifically in tumor blood vessels." (PMID 39001388, 2024). "Additionally, there were notable differences in CXCR4 protein expression between microsatellite instable (MSI) and microsatellite stable (MSS) tumor cell lines." (PMID 38464391, 2024). "Treatment of OSCC tumor bearing mice with the CXCR4 inhibitor AMD3100 revealed that CXCR4 inhibition induced tumor necrosis by suppressing intratumoral angiogenesis, suggesting the potential for molecular therapy targeting CXCR4-positive tumor blood vessels." (PMID 39001388, 2024). "The HMGB1 released from the necrotic tumor executes alarmin functions, activating tumor growth signaling via binding to a variety of receptors including TLR2/4, RAGE, and C-X-C motif chemokine receptor 4 (CXCR-4)." (PMID 37210579, 2023). "The combination of CXCR4 therapeutic agent blockade and PDCD1 resulted in the reduction of suppressive leukocytes and promoted the transition of M2-to-M1 macrophage polarization within the tumor." (PMID 38044943, 2023).
tumor (continued). "Previous studies have shown that CXCR4 mediates cancer cell adhesion, migration, chemoresistance, and metastasis, and small molecule or peptide inhibitors of CXCR4 such as AMD3100, TF14016, and LY2510924 decreased tumor growth and metastasis." (PMID 36597126, 2023). "Furthermore, STEAP4+, ADGRF5 + and CXCR4+, and SRGNC + fibroblast subgroups were closely related to tumor progression, tumor metabolism, and immunosuppression, indicating their contributions in PCa metastasis." (PMID 37221625, 2023). "CS extracts mitigate the CXCR4/PI3K/AKT signaling-mediated growth and metastasis capacities of OS cells, thus might play an anti-tumor role in OS." (PMID 38129870, 2023). "MDSCs have several chemokine receptors, including CCR1, CCR2, CCR3, CCR5, CCR12, CXCR2, CXCR4, and C5aR1.25In the current study, MDSCs may express CCR1, the receptor of CCL9, which mediated the migration of MDSCs to tumor tissue." (PMID 38046278, 2023). "These techniques would not allow to explore the expression levels of CXCR4 in the stroma without the sample being distorted by the expression of the protein in other cell subtypes, such as cells of the immune system or tumor cells." (PMID 37697316, 2023). "Except for CXCR6, all cytokines/cytokine receptors were shown to operate in the spine, with CX3CL1, CX3CR1, IL10, CCL2, CXCL12, and CXCR4 mediating bone marrow colonization, CXCL5 and TGFβ promoting tumor cell proliferation, and TGFβ additionally driving bone remodeling." (PMID 36835198, 2023). "B cells can capture tumor antigens and activate immune cells in the initial stage of the immune response, or participate in tumor killing by secreting antibodies, such as CCL2, CXCR4, CCL5, CXCL5 and CXCL10, which trigger the activation of CD4 and CD8 T cells." (PMID 37254219, 2023). "Additionally, responding patients had a lower tumor burden and displayed the expression of chemokine receptors (CCR7, CCR6, CXCR4, CXCR3, and CXCR5) on CD4+ T cells." (PMID 37174069, 2023). "We immunohistochemically stained the tumour samples against MSLN and CXCR4." (PMID 37047331, 2023). "These spots also upregulated the chemokines CXCL9 and CXCL12, which could attract T cells into the tumor via CXCR3 and CXCR4, respectively." (PMID 37655659, 2023). "We found that among our late-stage tumor cohort, 40 patients met the criteria of having negative/low tumor co-expression of MRP2/CXCR4/PD-L1 which, according to our results, translates into an inferior prognosis (HR = 2.62, median OS time of only six months)." (PMID 37444550, 2023). "The depletion of the FAP + stromal cells or inhibition of the receptor CXCR4 using AMD3100 could lead to rapid accumulation of CD8 + T cells and retard tumor growth." (PMID 38001512, 2023). "The binding of CXCL12 to CXCR4 is said to initiate divergent signaling pathways that lead to multiple responses, including the phosphorylation of MEK/ERK signaling cascade and the activation of NF-κB, which is essential for tumor cell survival." (PMID 36826044, 2023). "After the knockout of (the CXCR-4) gene using gene knockout technology, the adhesion ability of tumor cells was decreased, but the proliferation ability was not affected." (PMID 37020597, 2023). "In the context of the tumor microenvironment, SDC2 has been shown to be expressed on stromal cells within breast cancer tissue and positively modulates the transforming growth factor-β (TGF-β) signaling mainly through SMAD7, PAI-1, and CXCR4." (PMID 36980680, 2023). "AMD3100, a specific antagonist of CXCR4, is the most potent small-molecule non-peptide inhibitor of the CXCR4/CXCL12 axis via immune modulation in the tumor microenvironment." (PMID 36672284, 2023). "Moreover, EV can promote tumor lymphangiogenesis by intracellularly transferring lymphangiogenic factors VEGFC and CXCR4." (PMID 36671802, 2023).